IGF1 (insulin like growth factor 1)
Diseases named in the same sentence as IGF1 in open-access papers (continued):
Sharing a sentence is not in itself a finding about the gene and the disease.
tumor (continued). "Moreover, the conversion of energy metabolism results in dramatic downregulation of IGF-1 and upregulation of insulin-like growth factor binding protein-151 and increased tumor cell autophagy and programmed cell death." (PMID 33628585, 2021). "IGF1 expression in tumor tissues was 3-fold higher than that in normal tissues." (PMID 34253194, 2021). "Emphasizing the importance of modeling the tumor environment, Santoro and co-workers showed that culture of EwS cells on 3D scaffolds within a flow perfusion bioreactor promoted insulin-like growth factor-1 (IGF1) production and revealed shear stress-dependent resistance to an IGF-1R inhibitor." (PMID 33919988, 2021). "On the other hand, they did not evaluate the different subtypes of single staining group, including the percentage of SG adenoma, also their single staining group had fewer acromegalic features, lower IGF-1, prolactin levels, and smaller tumor size compared with dual staining one." (PMID 34530798, 2021). "Of interest, IGF-1 can increase activity of the PI3K pathway found in CSF-1R-resistant tumor cells." (PMID 34949203, 2021). "Insulin like growth factor-1 (IGF1) and estradiol were used as comparative tumor promoters to FGF2." (PMID 34685650, 2021). "Consistent high expression level of IGF-1 could be seen in normal tissues than most types of tumor based on both comparisons, and significant decreased expression of IGF-1 could be seen in tumor samples including ACC, BLCA, BRCA, CESC, CHOL, COAD, ESCA, LAML." (PMID 34804946, 2021). "Downregulation of IGF1/2 in combination with paclitaxel could reduce tumor cell proliferation and lung metastasis in pre-clinical BCa models." (PMID 33768092, 2021). "The activation of the mitogen-activated protein kinase and phosphoinositide 3-kinase pathways by IGF1 can enhance cell proliferation and inhibition of apoptosis, each of which could contribute to tumor development." (PMID 34858769, 2021). "Hence, these peptides are most likely able to downregulate other growth promoting factors of the tumor (e.g., gastrin and insulin-like growth factor 1 (IGF-1))." (PMID 34829972, 2021). "CAF secrete epidermal growth factor and insulin-like growth factor-1, which promote tumor growth." (PMID 34563225, 2021). "It has been reported that anamorelin elevates IGF-1, and IGF-1 promotes tumor growth." (PMID 34445197, 2021). "However, the size of the tumor increased to 6.4 cm, and serum GH and IGF-1 levels increased to 44.34 ng/mL and 507.77 ng/mL, respectively, 6 months after RAI therapy." (PMID 34461869, 2021). "Interestingly, the proteoglycan decorin acts as a tumor suppressor by binding and negatively regulating IGF1, IGF2, insulin, IGF1R and IR-A activity." (PMID 34440844, 2021). "Overexpression of miR-143 could reduce IGF-1-induced chemoresistance to docetaxel treatment and inhibit tumor growth in vivo." (PMID 33768092, 2021). "The role of IGF-1 in the development of tumor is a hot spot in current research." (PMID 34233689, 2021). "Furthermore, in the tumor-bearing mouse model, we detected low levels of IGF1 and TWIST1 expression in tumors originating from MCF-7 cells transfected with anti-RCC2 shRNA." (PMID 32565805, 2020). "We first examined the dynamic response of tumor OPCs to IGF1 or PDGFAA stimulation." (PMID 33173731, 2020). "IGF-1 promotes to product vascular endothelial growth factor, which supports tumor growth." (PMID 32709256, 2020). "Insulin and insulin-like growth factor 1 (IGF-1) may locally contribute to tumour cell proliferation." (PMID 32705315, 2020). "As the main binding protein of IGF-1, insulin-like growth factor binding protein-3 (IGFBP3) has been reported to be linked to pathogenesis of cancers by exerting tumor suppressor activity in breast cancer and pro-tumor effects in oral squamous cell carcinoma and lung cancer." (PMID 32312329, 2020).
tumor (continued). "As nutrient levels of BCAAs, substrates of BCATc, regulate the PI3K/Akt pathway we hypothesized that increased expression of BCATc would contribute to tumour cell growth through upregulation of the insulin/IGF-1 signalling pathway." (PMID 32523652, 2020). "IGF-1 signal transduction activates several downstream proteins involved in cell survival, proliferation, propagation, and confers radioresistance properties to tumor cells." (PMID 32708958, 2020). "KLF5 might inhibit cell invasion by suppressing the transcription of IGF1 in tumor cells and subsequently inhibiting its downstream activation of STAT3/MMP9." (PMID 32546700, 2020). "With regard to the prognostic factors, the FGFR2 SNP rs1219648 was associated with tumor differentiation (p-value = 0.018), the MAP3K1 SNP rs889312 was linked to the HER2 marker (p-value = 0.04), and the IGF1 SNP rs2373721 was correlated with progesterone receptor status (p-value = 0.04)." (PMID 33112566, 2020). "Taken together these data suggest that accelerated subcutaneous tumor growth within obese OVX mice is associated with an increase in subcutaneous adiposity and adipose inflammation, an IGF-1 rich subcutaneous microenvironment, and an increased presence of M2-like TAMs." (PMID 33346251, 2020). "However, in overweight patients, age (P = 0.015), tumor size (P = 0.020), and IGF-1 level (P = 0.038) are correlated with RFS in univariate models." (PMID 32391265, 2020). "In addition, tamoxifen prevents tumor growth by stimulating the tumor-inhibiting transforming growth factor B (TGFb) and downregulating the tumor-stimulating insulin-like growth factor 1 (IGF-1)." (PMID 33158297, 2020). "In addition, tumor cell progression is stimulated by enhancing the mTOR signaling pathways through an increase in insulin-like growth factor 1 (IGF-1)." (PMID 31959179, 2020). "Furthermore, IGF-1 promotes neutrophil polarization to a tumor promoting phenotype and the induction of a prometastatic microenvironment in the liver." (PMID 33339340, 2020). "In addition, metformin indirectly exerts an anti-tumor effect via reducing serum insulin level, repressing the signaling pathway of insulin and insulin-like growth factor 1 (I/IGF-1)/phosphoinositide 3-kinase (PI3K)/Akt/mTOR or I/IGF-1/Ras/Raf/MEK/ERK." (PMID 33382703, 2020). "In addition to tumor stem cells, some authors believe that IGF-1 is also an important stimulus for angiogenesis." (PMID 32899449, 2020). "In order to evaluate whether IGF-1 is produced by tumor and stromal cells, RT-qPCR analysis was performed in SCC-4 and primary human fibroblasts (MF1)." (PMID 32899449, 2020). "As magnolol increased the IGF-1 in macrophages, we next asked whether magnolol contributes to tumor growth and progression by recruiting M2-like macrophages into tumor microenvironment." (PMID 32117241, 2020). "First, the endogenous GH/IGF levels in WT mice could be adequate to drive tumor growth and may mask the effects of supraphysiological levels of GH or IGF-1." (PMID 33291663, 2020). "In order to evaluate whether stromal cells exert tumor-promoting activity through IGF-1, MF1 were genetically modified by a lentiviral system for IGF-1 overexpression, followed by characterization using RT-qPCR." (PMID 32899449, 2020). "Furthermore, TAM prevents the growth of tumours by upregulating the tumour-inhibiting transforming growth factor B (TGFb) and downregulating the tumour-stimulating insulin-like growth factor 1 (IGF-1)." (PMID 32151063, 2020). "Akin to their mouse counterparts, human tumor OPCs exhibited a strong preference for IGF1." (PMID 33173731, 2020). "However, subsequent studies found development of resistance to the CSF1R blockage through IGF1 secretion by TAMs resulting in resumed PI3K dependent tumor growth." (PMID 32555306, 2020).
tumor (continued). "IGF-1 participates in various growth-related pathways by altering protein structure or binding to the cell-matrix to regulate cell growth, differentiation, and nutrient metabolism, thereby influencing tumor cell division or anti-apoptotic pathways." (PMID 32370764, 2020). "IGF-1 has been shown to stimulate tumour angiogenesis as a result of increasing levels of VEGF." (PMID 33008076, 2020). "Therefore, IGF1 signaling axis likely plays essential roles in maintaining the stemness of tumor OPCs both in vitro and in vivo." (PMID 33173731, 2020). "In summary, we found that KLF5 deletion/downregulation in PCa could promote tumor invasion and metastasis through modulating the cytokine IGF1, expressed by tumor cells, and the subsequent cell signaling." (PMID 32546700, 2020). "Although the concentration of IGF2 in blood circulation is higher than that of IGF1, IGF1 plays a more important role in tumor progression than IGF2 because it is regulated by growth hormones, is not easily degraded, and has 15 times higher affinity with IGF1R." (PMID 32665850, 2020). "Since the really long-term effect of high-normal IGF-1 target levels during GH treatment remain to be investigated, and also the known suggested association with tumor progression, no clear recommendation on dosing strategy can be given at this moment." (PMID 33633687, 2020). "Taken together, these results suggest that Plasmodium infection might reduce MMP-9 and IGF-1 expression in TAMs and tumor tissue and that this effect is responsible for the reduced angiogenesis within tumors." (PMID 32972437, 2020). "Besides, circPLK1 knockdown suppressed tumor growth via upregulating miR-4500 and downregulating IGF1." (PMID 33298061, 2020). "Despite changes in tumor gene expression and increased cell growth in response to GH treatment in vitro, we did not observe increased tumor growth or size due to excess GH or IGF-1 in vivo." (PMID 33291663, 2020). "Addition of IGF-1 could recover the suppressive impact of silenced ZEB1-AS1 on tumor growth, volume and weight." (PMID 32231464, 2020). "Contrarily, circulating IGF‐1 isoforms can induce hyperplasia and spontaneous tumor formation." (PMID 30953403, 2019). "For patients who are biochemically resistant to first-generation SRLs, the addition of cabergoline may be useful as SRLs could maintain long-term effects on tumour mass, while cabergoline may lower IGF-1 levels." (PMID 31939490, 2019). "No significant interclass differences were detected in age, sex, random GH level, nadir GH level and GH inhibition ratio following a glucose load, insulin-like growth factor 1 level, tumor volume, or Knosp classification between the two cohorts (p = 0.418–0.999)." (PMID 31316464, 2019). "Moreover, KD regulates insulin and tumor related growth factors (like insulin growth factor-1, IGF-1)." (PMID 31398922, 2019). "This ‘experiment of nature’ reflects the critical role of IGF1 in tumor biology." (PMID 31208077, 2019). "In addition, previous findings showed that in rat tumour Leydig cells, IGF-1 had the ability to activate c-Jun28." (PMID 31076571, 2019). "The present review article provides an overview of recently conducted genome-wide profiling analyses aimed at identifying mechanisms and signaling pathways that are directly responsible for the link between life-time low IGF1 levels and protection from tumor development." (PMID 31208077, 2019). "However, the mean GH, IGF-1 levels and tumor volume decreased significantly in both the groups following surgery." (PMID 30948746, 2019). "Also, an over-expression of IGF-1/IGF-1R signaling also contributes to tumor cell survival, metastasis, and resistance to chemotherapy protocols." (PMID 30881341, 2019). "Furthermore, in human clinical samples, we found that IGF-1 was abundant in the tumour stroma CAFs in RC tissues from the pNR group." (PMID 31076571, 2019).
tumor (continued). "However, the mean GH, IGF-1, tumor volume and anterior pituitary hormone status were comparable in both the groups." (PMID 30948746, 2019). "Furthermore, we observed that overexpression of COL6A6 significantly decreased the size of the tumor compared with the control group (all P<0.001), while the size of the tumor with IGF-1 treatment was bigger than the COL6A6 overexpression group (all P<0.001)." (PMID 31627190, 2019). "Furthermore, the suppression of the stemness phenotypes including migration and tumor sphere formation, apoptosis induction, and cell cycle arrest evoked by zoledronic acid in HeLa cells derived CSCs were also attenuated after IGF-1 treatment." (PMID 30791957, 2019). "Furthermore, only 2 of the patients with tumours with score 1 (of 20) displayed an IGF1 decrease higher than 50% at 3 months of SSAs treatment, and only 1 of 17 at 6 months after treatment." (PMID 30843342, 2019). "Insulin stimulates the synthesis of IGF-1 and leads to tumor growth." (PMID 30636976, 2019). "However, it is described in the literature that SSA can trigger indirect tumor suppressive effects via further growth hormones and IGF1." (PMID 31237925, 2019). "IGF‐1 mRNA expression was more potently induced by IL‐4 than by LPS, in agreement with its proposed role as marker for wound‐healing macrophages, which contribute to tumor progression." (PMID 29907597, 2018). "In another experiment, we showed that a single DB pre-treatment (below IC50) could significantly reduce the tumor-initiating ability of IGF1-cultured DLD-1 colon CSC-like cells in vivo." (PMID 30257507, 2018). "Similarly, the IGF-1/IGF-1R axis can stimulate other concurrent oncogenic mechanisms in tumor cells, such as androgen receptor signaling in prostate and in colon cancer cells." (PMID 30111747, 2018). "In this study, we revealed that epidermal IGF-1 production, which is required for efficient wound healing, could be downregulated by IL-17A after skin injury." (PMID 29483920, 2018). "More importantly, we demonstrated that IGF1 treatment promoted tumor initiation in vivo." (PMID 30257507, 2018). "Additionally, flaxseed oil was found to reduce MCF-7 tumor growth partially through IGF-1 signaling pathway." (PMID 29323210, 2018). "Several studies suggest that the imbalance between serum levels of IGF-1 and IGFBP3 could trigger abnormal cell proliferation, increasing the risk of neoplastic diseases." (PMID 30643822, 2018). "The TMA was stained for IGF-1, and ILC tumours exhibited significantly higher cytoplasmic expression of IGF-1 compared to IDC tumours; the median histoscore for IGF-1 was 140 (interquartile range, 59.7–205.8) in ILC and 103.8 (interquartile range, 16.5–131.0) in IDC (P = 0.0408)." (PMID 30337563, 2018). "A recent study showed that IGF1 production by myeloid-derived suppressor cells promoted stromal cell migration and tumor invasion, implying that IGF1 might also play a role in the tumor-promoting effect of myeloid-derived suppressor cells." (PMID 29922232, 2018). "For example, tumor progression from xenografts taken from a variety of mouse transgenic breast cancer strains (mouse mammary tumor virus (MMTV) -Neu, c-Myc or vascular endothelial growth factor (VEGF)) is accelerated in IGF1 deficient mice." (PMID 30567377, 2018). "Furthermore, growth factors and cytokines like TGFβ, PDGF and IGF1 are released during osteolysis, which have a proliferation inducing effect on tumor cells and additionally promote bone metastasis progression." (PMID 29644008, 2018). "The most significantly enriched pathways included ones that are known to be associated with tumor cell proliferation and migration, such as the TGF-β, IGF-1 and ERK5 signaling pathways, and pathways involved in energy generation: Glycolysis and pyridoxal 5′-phosphate (PLP) salvage pathways." (PMID 30423977, 2018).
tumor (continued). "There may well be inter‐racial heterogeneity in tumor grades or serum levels of IGF‐1, IGFBP‐3, or testosterone, and therefore external validation of our findings using a larger cohort is warranted." (PMID 29992746, 2018). "A higher Knosp score was associated with larger tumour diameter, but not with any other study parameter, including IGF-1 levels." (PMID 29670116, 2018). "FOXP2 may also participate in modulating the expression of various genes involved in tumor signaling pathways, including IGF-1 (insulin-like growth factor 1), NF-ĸB (nuclear factor kappa-light-chain-enhancer of activated B cells), and Wnt." (PMID 30360388, 2018). "In addition, it has been shown that rapamycin (an mTOR inhibitor) prevents both cell adhesion and F-actin reorganization induced by insulin-like growth factor 1 (IGF-1) in different tumor cell lines." (PMID 30073169, 2018). "As the anti-tumor effect of cisplatin relies on its DNA damage properties, DNA repairing mediated by IGF-1 might lead to reduced sensitivity to cisplatin." (PMID 30241323, 2018). "No other significant correlations between SSTR or DRD expression and age, tumour size and GH or IGF‐1 levels (assessed by per cent increase from the upper limit of normal) could be identified." (PMID 29266696, 2018). "Their results indicated that engaging the IGF-1/IGF-1R system might enable tumor cells to escape anti-EGFR-mediated treatment as a consequence of IGF-1-driven stimulation of the PI3K–Akt pathway." (PMID 28423026, 2017). "A heat map of gene expression levels in tumors, ordered in descending order, on the basis of the phosphorylated IGF1R signal, provided a visualization of the expression profile of IGF pathway genes in each tumor, and highlighted the mutually exclusive nature of IGF1 and IGF2 expression." (PMID 28882129, 2017). "Therefore, IGF1 and insulin more likely (at lower concentrations) enhance tumour cell survival than proliferation, via activation and maintenance of phosphatidylinositol 3-kinase activity and p-Akt/PKB." (PMID 28316059, 2017). "In particular, in these patients, a combined SRL–PEG treatment might be proposed to normalize GH/IGF-1 secretion waiting for a possible delayed SRL effect on tumor mass." (PMID 28176221, 2017). "TABCs play a positive role in tumor growth and, particularly in tumor chemoresistance through the release of the growth factor insulin-like growth factor 1 (IGF-1), mediating the appearance of heterogeneous tumor cell populations resistant to BRAF and/or MEK inhibitors." (PMID 29156643, 2017). "A patient with GH/IGF-1 reduction <50% and/or tumor mass shrinkage <20–25% may be considered as SRL-resistant." (PMID 28176221, 2017). "Such host factors include systemic metabolic regulators including insulin, insulin-like growth factor 1, adipokines, inflammation-related molecules, and steroid hormones, as well as the cellular and structural components of the tumor microenvironment, particularly adipose tissue." (PMID 28959684, 2017). "Several studies showed that anti-IGF-1 inhibits tumor growth." (PMID 29255466, 2017). "Since mice were chronically exposed to insulin analogues that activate (to a lesser or greater extent) the IGF1R, we postulated that the decreased tumor latency time (after X10/IGF1 stimulation) would be a direct result of an upregulated IGF1R signaling pathway." (PMID 28173837, 2017). "Insulin or IGF-1 treatment stimulates the proliferation of tumor cells." (PMID 28978182, 2017). "Considering the important role of IGF-1 in tumor progression, we examined whether IGF-1 was responsible for the tumor growth advantage with IL-15 stimulation." (PMID 29255466, 2017). "In addition, we showed that IGF-1 is more weakly expressed in NPC cell lines and tumour tissues and that decreasing serum levels of IGF-1 are observed in NPC patients." (PMID 28143425, 2017). "Tumor-conditioned fresh NB cells showed a similar increase in IGF-1." (PMID 28928360, 2017).